TSSK1B (testis specific serine kinase 1B)
Description:
Testis-specific serine/threonine-protein kinase required during spermatid development. Phosphorylates 'Ser-288' of TSKS. Involved in the late stages of spermatogenesis, during the reconstruction of the cytoplasm. During spermatogenesis, required for the transformation of a ring-shaped structure around the base of the flagellum originating from the chromatoid body.
Synonyms: TSK1; SPOGA4; STK22D; TSSK1; FKSG81
Tractability: Small molecule: a high-quality ligand is known; it belongs to a druggable protein family. PROTAC: UniProt records ubiquitination sites on it; a small molecule that binds it is known.
Target class: CAMK protein kinase TSSK family; CAMK protein kinase group; Protein Kinase; Enzyme; Kinase
Gene: Protein-coding gene on chromosome 5 (113,432,553 to 113,434,989, reverse strand). Ensembl gene ENSG00000212122.
Subcellular location: Cytoplasm; Cytoplasmic vesicle, secretory vesicle, acrosome; Cell projection, cilium, flagellum
Subcellular location (Human Protein Atlas): Nuclear bodies; Principal piece; Annulus; Basal body; Centrosome; End piece; Perinuclear theca
Gene Ontology:
Molecular function: ATP binding; magnesium ion binding; protein binding; protein serine kinase activity; protein serine/threonine kinase activity; protein kinase activity; protein-containing complex binding
Biological process: spermatid development; gene expression; skin development
Cellular component: motile cilium; acrosomal vesicle; cytoplasm
Genetic constraint (gnomAD): Loss-of-function variants: 5 observed, 7.08 expected, observed/expected ratio (o/e) 0.71, 90% interval 0.37 to 1.46. That is too few expected variants to judge how well the gene tolerates losing a copy. Missense variants: 488 observed, 520.58 expected, observed/expected ratio (o/e) 0.94, 90% interval 0.87 to 1.01. Synonymous variants: 198 observed, 211.77 expected, observed/expected ratio (o/e) 0.93, 90% interval 0.83 to 1.05.
Homologues: Orthologues: mouse Tssk1 (84% identical), pig TSSK1 (84% identical), dog TSSK1 (83% identical), rabbit TSSK1B (74% identical), Caenorhabditis elegans C27D6.11 (30% identical), Caenorhabditis elegans tag-344 (29% identical), Caenorhabditis elegans Y38H8A.4 (29% identical). Paralogues in human: TSSK2 (66% identical), NUAK1 (35% identical), NUAK2 (35% identical), SIK2 (35% identical), SIK1 (35% identical), TSSK3 (35% identical), TSSK6 (34% identical), TSSK4 (34% identical), SIK3 (33% identical), HUNK (31% identical), SNRK (31% identical), PRKAA2 (30% identical), and 5 more.
Diseases named in the same sentence as TSSK1B in open-access papers:
TSSK1B is named in the same sentence as 14 diseases in open-access papers, as found by Europe PMC text mining. Sharing a sentence is not in itself a finding about the gene and the disease. The quoted sentences say what the papers report.
male infertility (2 papers, 2018 to 2022). The inability of the male to effect fertilization of an ovum after a specified period of unprotected intercourse. "Previous studies suggested that disruptions of CAMK4 located on chromosome 5q22.1, SPINK13 located on chromosome5q32 and the testis-specific serine/threonine kinase (TSSK1B) gene mapped to chromosome 5q22.2 were associated with loss of sperm function and human male infertility." (PMID 29416565, 2018).
cancer (2 papers, 2020 to 2024). A tumor composed of atypical neoplastic, often pleomorphic cells that invade other tissues. "Assessing the expression levels and activity of TSSK1B in cancer tissues becomes crucial in evaluating its therapeutic potential." (PMID 38245531, 2024). "While our study identified TSSK1B’s impact on cellular proliferation and oncogenic transformation, further exploration is needed to gauge the clinical relevance of targeting TSSK1B for cancer therapy." (PMID 38245531, 2024). "Eight understudied kinases were found to have hotspot mutations in at least one cancer (CDC42BPA, DYRK1B, DYRK4, LMTK3, MAPK15, NEK7, TSSK1B, and TTBK1), with DYRK4, LMTK3, MAPK15, and NEK7 all having significant hotspot mutations in STAD." (PMID 33205077, 2020). "By targeting the dysregulated Hippo signaling pathway through interventions that leverage the regulatory role of TSSK1B, we may pave the way for future therapeutic approaches against cancer." (PMID 38245531, 2024).
tumor (1 paper, 2024). "In light of our data, we have discovered that TSSK1B functions as an anti-tumor regulator by phosphorylating and inhibiting the oncogenic activity of YAP." (PMID 38245531, 2024). "Time-course regression analyses demonstrated that TSSK1B WT induces slower tumor growth and considerably smaller tumor burden compared to the control and TSSK1B mutant (T174A), without significant toxicity or weight loss." (PMID 38245531, 2024). "To validate our findings in vivo, we subcutaneously injected MEF Lats1/2 KO cells stably expressing TSSK1B WT and TSSK1B mutant (T174A) cells into BALB/c nude mice (N = 6) and monitored tumor development." (PMID 38245531, 2024).
TSSK1B also shares sentences with these, for which no sentence is quoted: fibrosis (5 papers); infertile (2); scleroderma (2); systemic scleroderma (2); colorectal cancer (1); infection (1); interstitial lung disease (1); lung disease (1); Marfan syndrome (1); pulmonary fibrosis (1); stiff skin syndrome (1).